BMP4 (bone morphogenetic protein 4)
Diseases named in the same sentence as BMP4 in open-access papers (continued):
Sharing a sentence is not in itself a finding about the gene and the disease.
ovarian carcinoma (31 papers, 2008 to 2025). A malignant neoplasm originating from the surface ovarian epithelium. "Similarly, it has been reported that OC cell-derived SHH induced human ovarian carcinoma-associated mesenchymal stem cells to express BMP4, which promoted chemotherapy resistance in OC." (PMID 28978035, 2017). "Elevated OCT4 promotes ovarian cancer cell proliferation and growth by upregulating bone morphogenetic protein 4 (BMP4) and interacting with Lin28." (PMID 39633710, 2024). "They demonstrated that Hedgehog secreted by ovarian cancer cells induces BMP4 expression in MSCs, which leads to the increased expression of Hedgehog in ovarian cancer cells, indicating a positive feedback loop." (PMID 35954425, 2022). "Overexpression of BMP4 is related to the invasion and migration of melanoma cells and ovarian cancer cells." (PMID 32224866, 2020). "However, a previous report suggests that cancer stem cells in ovarian cancer may be derived from GSCs, and cancer-associated mesenchymal stem cells (the niche for cancer stem cells) express a high level of BMP4, which promotes tumor growth by increasing the number of cancer stem cells." (PMID 30122445, 2018). "The EGF-EGFR axis promotes CDCP1 expression in ovarian cancer models, and bone morphogenetic protein 4 induces CDCP1 in pancreatic cancer cells." (PMID 29792166, 2018). "A recent study showed that LIN28A binds to bone morphogenetic proteins 4 (BMP4) mRNA promoting its expression at a post-transcriptional level in ovarian cancer cells." (PMID 28400788, 2017). "Taken together, our study warrantee further investigation to define the mechanisms by which SENP1-SUMO mediates BMP4 gene expression, which will provide potential therapeutic targets for human POI and other ovarian associated diseases such as ovarian cancer." (PMID 28770041, 2017). "To investigate this possibility, we treated ovarian cancer cells with recombinant BMP4 and analyzed SHH expression via qRT-PCR." (PMID 26755648, 2016). "BMP4 promotes migration and metastasis in ovarian cancer and BMP4 stimulation of ovarian cancer cells can activate ID3 proto-oncogene expression." (PMID 26755648, 2016). "CA-MSC-derived BMP4 reciprocally increases HH production in ovarian cancer cells thus creating a positive feedback loop between the tumor and CA-MSCs." (PMID 26755648, 2016). "Collectively, we define a critical positive feedback loop between CA-MSC-derived BMP4 and ovarian tumor cell-secreted HH and present evidence for the further investigation of HH as a clinical target in ovarian cancer." (PMID 26755648, 2016). "We therefore investigated the role of CA-MSCs and the tumor/stromal HH/BMP4 signaling loop in resistance to platinum based chemotherapy, the core of ovarian cancer therapy." (PMID 26755648, 2016). "Previous studies have also associated BMP2 and BMP4 with ovarian cancer, both of which are expressed at extremely low levels in tumor cells and TAMs, which may be explained by the previous identification of ovarian cancer-associated mesenchymal stem cells as a major source of these cytokines." (PMID 27215396, 2016). "In ovarian cancer, TGF-β and BMP4 are reported to play an important role in controlling ovarian cancer metastasis." (PMID 26239324, 2015). "BMP4 in ovarian cancer cells induces EMT via the (BMP4)/anaplastic lymphoma kinase (ALK) pathway, increasing the expression of mRNA and protein levels of Snail and Slug and downregulating E-cadherin." (PMID 26356073, 2015). "Previous work from our laboratory demonstrated that normal human ovarian surface epithelial (OSE) cells and human epithelial ovarian cancer (EOC) cells possess an intact autocrine bone morphogenetic protein-4 (BMP4) signalling pathway." (PMID 20187934, 2010). "A recent study has demonstrated the involvement of BMP-4 in the epithelial mesenchymal transition in human ovarian cancer cells." (PMID 19366455, 2009).
ovarian carcinoma (continued). "In addition, BMP4 signaling causes direct overexpression of ID3, a proto-oncogene that contributes to the pathogenesis of human ovarian cancer." (PMID 28947976, 2017). "For instance, in breast epithelial and ovarian cancer cells, BMP-4 could induce EMT by decreasing E-cadherin, increasing N-cadherin, disrupting the polarity of ZO-1, and inducing transcription factors, Slug and Snail, to facilitate tumor progression." (PMID 27661009, 2016). "Several studies have supported a critical role for BMP4 in ovarian cancer." (PMID 26755648, 2016). "In ovarian cancer, human carcinoma-associated mesenchymal stem cells could increase the number of CSCs and promote the chemotherapy resistance of ovarian cancer by activating the BMP-4/Hedgehog signaling pathway." (PMID 27661009, 2016). "In compare to the mesenchymal stromal cells (HOTC) of normal ovarian tissue, we have shown that mesenchymal like cancer tumor fibroblasts (HOCTC) sprouting from ovarian cancer tissue expressed higher levels of BMP2, BMP4 and TGF-β, which are highly associated with tumorigenesis and metastasis." (PMID 22330345, 2012). "On the other hand, Bmp4 has been shown to induce EMT in human ovarian cancer cells." (PMID 19424481, 2008). "Lin-28 is reported to regulate BMP4 in ovarian cancer; this study hypothesized that BMP4, a growth factor that is highly produced in ovarian cancer cells, or BMPs derived from ovarian CA-MSCs, may stimulate CSC/TIC proliferation and thereby promote tumor growth." (PMID 23528891, 2013). "BMPs belong to the TGF-β superfamily, and dysregulated BMP4 expression is known to affect follicular development, PCOS pathogenesis, and even ovarian cancer." (PMID 41585802, 2025). "BMP4 was shown to be downregulated in bladder cancer, where better progression-free survival (PFS) was observed in advanced ovarian cancer patients with strong expression of BMP-4." (PMID 33672869, 2021). "In contrast, BMP4 promotes prostate tumor growth and induces EMT in pancreatic and ovarian cancer cells." (PMID 26395571, 2015). "In the presents study, TMEM158 knockdown significantly decreased the expression of TGF-β and BMP4, which indicated a relation between TMEM158 function and the regulation of TGF-β signaling in ovarian cancer cells." (PMID 26239324, 2015). "Factors such as endothelin A receptor/endothelin-1 axis, autocrine BMP4 signaling pathway, and 17ß-estradiol have been reported to trigger EMT and promote tumor progression by up-regulating Snail1 activity in human ovarian cancer cells." (PMID 21559368, 2011). "Similar effects with BMP-4, as observed here with BMP-2, have recently been reported in ovarian cancer cell lines and ovarian cancer primary cultures." (PMID 19366455, 2009). "In ovarian cancer, overexpression of BMP-2, BMP-4 and BMP-7 mRNAs have been reported as dysregulated by microarray analyses." (PMID 19366455, 2009). "Additionally, T-MSCs promoted the proportion of CSCs, as observed in ovarian cancer cell, probably because of upregulation of bone morphogenetic proteins (BMPs), such as BMP2, BMP4, and BMP6 in ovarian cancer-derived MSCs." (PMID 31555593, 2019). "In the COV318 ovarian cancer cell line, BMP4 treatment induced IHH rather than SHH." (PMID 26755648, 2016). "In the same way, BMP-4 has also been reported to slightly reduce the proliferation of SKOV3 ovarian cancer cells, as well as some primary cultures of ovarian cancer cells while other ovarian primary cultures were not sensitive to this protein." (PMID 19366455, 2009).
atherosclerosis (30 papers, 2012 to 2025). A disease characterized by the build-up of fatty material and calcium deposition in the arterial wall resulting in partial or complete occlusion of the arterial lumen. "Using two types of BMP4-DKO mouse models, our previous study found that deficiency of BMP4 in PVAT aggravated atherosclerosis development in ApoE–/– mice." (PMID 36457800, 2022). "More importantly, BMP4 deficiency in adipose tissues exacerbates atherosclerosis, while BMP4 overexpression in adipose tissues promotes PVAT browning and atheroprevention in ApoE-/- mice." (PMID 36172381, 2022). "BMP4 is increased in response to a high fat diet (a risk factor for atherosclerosis), which then up-regulates BMP2 levels." (PMID 28646109, 2017). "Instead, the trend showcased by the TGF-β1/BMP-4 expression ratio was the opposite, highlighting the role of these two complexes in the development of atherosclerosis." (PMID 39768183, 2024). "Pretreatment with BMP4 abrogated PVAT induced upregulation of PPARγ, ABCA1 and ABCG1, further confirming the role of BMP4 in atherosclerosis." (PMID 39327610, 2024). "Bone morphogenetic protein 4 (BMP4) has been reported as a browning regulator of tPVAT protecting the thoracic artery against atherosclerosis." (PMID 39156105, 2024). "Another study found that BMP-4 drives inflammation upon low wall shear stress in the arteries during the early stage of atherosclerosis." (PMID 36909186, 2023). "Previous studies found that the level of BMP-4 was elevated in the aortic wall in an atherosclerosis mouse model." (PMID 36909186, 2023). "Our previous study indicates that loss of BMP4 in PVAT impaired PVAT metabolism and accelerated the development of atherosclerosis in ApoE–/– mice." (PMID 36457800, 2022). "Our findings identify platelet BMP-4 as a mediator of vascular inflammation in early atherosclerosis and restenosis." (PMID 34440796, 2021). "BMP-4 represents the earliest measurable marker of atherosclerosis and is considered to be a mechanically sensitive autocrine cytokine, which plays an important role in promoting inflammation, hypertension and atherosclerosis." (PMID 33684162, 2021). "Conversely, abnormal levels of BMP4 in adulthood are correlated with vascular dysfunctions including calcification, atherosclerosis and vascular leakage." (PMID 32896271, 2020). "During the development of atherosclerosis, BMP4 produced in endothelial cells, which then leads to ICAM-1 induction and monocyte binding." (PMID 31064817, 2019). "BMP4 accelerate the progression of atherosclerosis by induced macrophage foam cell formation through BMPR-2/Smad1/5/8 signaling." (PMID 31064817, 2019). "As NBL1 is a specific antagonist of BMP2 and BMP4, both of which promote atherosclerosis, NBL1 is capable to inhibit atherosclerosis." (PMID 29596467, 2018). "Other studies suggest that BMP2 and BMP4 are linked to the development of atherosclerosis, and BMP antagonist neuroblastoma suppressor of tumorigenicity 1 (NBL1, accession number X66872.1) specifically antagonizes BMP2, BMP4 and BMP14." (PMID 29596467, 2018). "In conclusion, we have demonstrated that BMP4 is expressed in monocytes/macrophages in atherosclerotic plaques in a mouse model of diabetes and atherosclerosis." (PMID 24107300, 2013). "Other BMPs, which have antagonistic properties, are coexpressed with BMP4 in mouse aortas and in human coronary arteries, suggesting that BMPs, including BMP4, are involved in the formation of atherosclerosis." (PMID 24107300, 2013). "BMP4 was also reported to mediate monocyte adhesion, which is enhanced in atherosclerosis, restenosis, and diabetes." (PMID 24107300, 2013). "Levels of HSP70, bone morphogenetic protein-4, and IL-6 were all elevated within the aortic wall as well as the serum in a mouse model of atherosclerosis." (PMID 23304456, 2012).
atherosclerosis (continued). "In contrast, BMP4 deficiency leads to a phenotypic shift of PVAT toward white adipose characteristics, accompanied by increased macrophage infiltration, endothelial activation, and exacerbated atherosclerosis." (PMID 40861271, 2025). "Therefore, a subgroup of hepatic Bmp4+Selp+-VECs from cluster 2 was revealed, and they were probably involved in the regulation of fibrosis and atherosclerosis in NASH." (PMID 38461242, 2024). "It well-known that the expression of BMPR-2, the receptor for classic osteogenic ligands BMP-2 and BMP-4, is decreased in patients with advanced coronary atherosclerosis and it is protective against atherosclerosis in animal models, suggesting a context-specific role of BMPR-2-mediated signalling." (PMID 39768183, 2024). "However, the role of BMP-4 in the progression to advanced atherosclerosis depends on other mechanisms, such as different contexts and different tissue and cell types." (PMID 36909186, 2023). "Similarly, elevated levels of other BMPs such as BMP4, BMP7, BMP9 were associated with atherosclerosis, hepatic cancer, and metabolic syndrome respectively." (PMID 38127951, 2023). "Further studies are needed to identify the role of BMP-4 in advanced atherosclerosis." (PMID 36909186, 2023). "In addition, our previous study demonstrated that BMP4 in PVAT exerts protective effects on atherosclerosis by activating PVAT metabolism, suggesting BMP4 -activated PVAT metabolism exerts beneficial effects on cardiovascular system." (PMID 36457800, 2022). "Similarly, BMP-4, BMP-10, and BMP-7 have been implicated in cardiovascular physiology and pathology, including vascular inflammation, atherosclerosis, and calcification; however, their prognostic value for systemic cardiovascular risk in patients with PAD has not been established." (PMID 40710778, 2025). "In addition, it is unclear whether the protective effect of platelet BMP-4 is only limited to the early phase of acute vascular injury or has a long lasting effect in chronic vascular inflammation, e.g., atherosclerosis." (PMID 34440796, 2021). "Therefore, our results will provide a new insight about how BMP4 accelerate the progressio of atherosclerosis, and it may become a potential target against atherosclerosis and its complications." (PMID 24690996, 2014). "HOXA5 safeguards against atherosclerosis via peroxisome proliferator-activated receptor gamma (PPARγ), whereas HOXB9 exacerbates inflammation through bone morphogenetic protein 4-tumor necrosis factor (BMP4-TNF)." (PMID 41181801, 2025). "Conversely, overexpression of BMP4 stimulates the browning of PVAT, inhibits inflammatory responses, and hampers the development of atherosclerosis." (PMID 38784129, 2024). "Other important pathways for endothelial homeostasis that were disrupted included inflammatory pathways (for example, atherosclerosis, agranulocyte adhesion and diapedesis) represented by the upregulation of genes such as ICAM1, BMP4 and IL6." (PMID 26617239, 2015). "Therefore, BMP4 may become a potential agent against atherosclerosis and its complications." (PMID 24690996, 2014). "The absence of BMP4 in PVAT reduces BAT-characteristic gene expressions, increases pro-inflammatory mediators, and exacerbates atherosclerosis plaque formation, while activation of BMP4 signaling reverses these pathological features in ApoE−/− mice." (PMID 38784129, 2024).
hepatocellular carcinoma (26 papers, 2010 to 2024). A malignant tumor that arises from hepatocytes. "BMP4-induced epithelial mesenchymal transition through upregulation of ID2 and promoted metastasis in hepatocellular carcinoma, which was associated with poor prognosis in patients with 420 paired HCC study." (PMID 37443106, 2023). "It was reported that BMP4 was highly expressed in hepatocellular carcinoma and promoted the malignant phenotype of the tumor." (PMID 37443106, 2023). "It has also been reported that BMP4 is located upstream of autophagy, and it can promote the proliferation of hepatoma cells as well as increase the resistance to leukemic chemotherapy drugs by activating autophagy, subsequently inhibiting apoptosis." (PMID 36618911, 2022). "BMP4 promotes hepatocellular carcinoma proliferation through JNK1-mediated autophagic activation of Bcl-2 phosphorylation." (PMID 34221974, 2021). "In any case, upregulation of SMAD9 due to BMP4 treatment has also been recently reported in various cell types, for example in primary fibroblasts, hepatocellular carcinoma and melanoma cells." (PMID 28077088, 2017). "For example, BMP4 induces differentiation of cancer stem cells, blocks progression of hepatocellular carcinoma, and suppresses tumorigenesis of gastric carcinoma." (PMID 26395571, 2015). "In our previous study, we found that BMP4 augments the survival of hepatocellular carcinoma (HCC) cells under hypoxia and hypoglycemia conditions by promoting the glycolysis pathway." (PMID 37443106, 2023). "We previously reported that BMP4 has the strongest ability to promote glycogenesis among the 14 BMPs in hepatocytes and augmented hepatocellular carcinoma (HCC) cell survival under hypoxia and hypoglycemia conditions by promoting the glycolysis pathway." (PMID 37443106, 2023). "However, whether BMP4 contributes to the regulation of autophagy in hepatocellular carcinoma (HCC) progression remains elusive." (PMID 30012194, 2018). "Furthermore, BMP4 promotes differentiation of hepatocellular carcinoma (HCC) cancer stem cells." (PMID 29295498, 2017). "The correlation of BMP-4 expression with clinical aggressiveness and prognosis in hepatocellular carcinoma (HCC) has also been reported." (PMID 24779016, 2014). "Studies examining hypoxia dependent transcription of BMP4 in hepatocellular carcinoma cells (HCC) showed that HIF1α dependent regulation of BMP4 expression is indirect in these cells." (PMID 20585586, 2010). "Upregulation of BMP4 and BMPR1A in HCC was shown to promote proliferation and metastasis of hepatocellular carcinoma cells through activation of the MEK/ERK signaling pathway." (PMID 37443106, 2023). "However, the effect of BMP4 on glycogen synthesis in hepatoma cells is still unknown." (PMID 37443106, 2023). "Bone morphogenetic protein 4 (BMP4), a member of the TGF-β superfamily, was overexpressed in drug-resistant hepatocellular carcinoma (HCC)." (PMID 36313710, 2022). "In hepatocellular carcinoma (HCC), several BMPs (BMP-4, -6, -7, -8, -9, -10, -11, -13, and -15) revealed enhanced expression levels." (PMID 27661009, 2016). "Mix.1 is induced in Xenopus embryos by BMP4 or activin A in a SMAD5-dependent manner, and MIXL1 can be induced by TGF-β in human hepatocellular carcinoma and in mouse embryonic stem cells." (PMID 25544748, 2014). "We demonstrate that BMP4 stimulates HCV RNA replication and antagonizing VEGF-A in the LSEC-hepatoma coculture promotes viral replication." (PMID 23775568, 2014). "Whereas BMP4 and BMP7 were up-regulated in cirrhosis, BMP4 and BMP7 along with SRC were further up-regulated in hepatocellular carcinoma." (PMID 23991421, 2013). "Hence, understanding the possible role of BMP4 in regulating hepatic glycometabolism during the development and progression of hepatocellular carcinoma may aid us to identify new therapeutic targets for HCC treatment." (PMID 37443106, 2023).